ATP6V0E2 (ATPase H+ transporting V0 subunit e2)
Description:
Subunit of the V0 complex of vacuolar(H+)-ATPase (V-ATPase), a multisubunit enzyme composed of a peripheral complex (V1) that hydrolyzes ATP and a membrane integral complex (V0) that translocates protons (By similarity). V-ATPase is responsible for acidifying and maintaining the pH of intracellular compartments and in some cell types, is targeted to the plasma membrane, where it is responsible for acidifying the extracellular environment (By similarity).
Synonyms: ATP6V0E2L; C7orf32
Tractability: Antibody: UniProt predicts a signal peptide or a membrane-spanning region.
Gene: Protein-coding gene on chromosome 7 (149,872,968 to 149,891,204, forward strand). Ensembl gene ENSG00000171130.
Subcellular location: Membrane; Cytoplasmic vesicle, clathrin-coated vesicle membrane; Cytoplasmic vesicle, secretory vesicle, synaptic vesicle membrane
Pathways (Reactome):
Transport of small molecules: Ion channel transport; Transferrin endocytosis and recycling
Cellular responses to stimuli: Amino acids regulate mTORC1
Developmental Biology: Regulation of MITF-M-dependent genes involved in lysosome biogenesis and autophagy
Immune System: ROS and RNS production in phagocytes
Signal Transduction: Insulin receptor recycling
Gene Ontology:
Molecular function: proton-transporting ATPase activity, rotational mechanism; ATPase-coupled ion transmembrane transporter activity
Biological process: proton transmembrane transport; regulation of macroautophagy; vacuolar acidification
Cellular component: endosome membrane; lysosomal membrane; membrane; phagocytic vesicle membrane; vacuolar proton-transporting V-type ATPase, V0 domain; clathrin-coated vesicle membrane; proton-transporting V-type ATPase, V0 domain; synaptic vesicle membrane
Genetic constraint (gnomAD): Loss-of-function variants: 4 observed, 9.41 expected, observed/expected ratio (o/e) 0.43, 90% interval 0.21 to 0.97. That is too few expected variants to judge how well the gene tolerates losing a copy. Missense variants: 93 observed, 111.93 expected, observed/expected ratio (o/e) 0.83, 90% interval 0.7 to 0.99. Synonymous variants: 52 observed, 49.24 expected, observed/expected ratio (o/e) 1.06, 90% interval 0.84 to 1.33.
Homologues: Orthologues: macaque ATP6V0E2 (99% identical), rat Atp6v0e2 (99% identical), guinea pig ATP6V0E2 (98% identical), rabbit ATP6V0E2 (98% identical), pig ATP6V0E2 (96% identical), zebrafish atpv0e2 (78% identical), chimpanzee ATP6V0E2 (68% identical), mouse Atp6v0e2 (68% identical), Drosophila melanogaster VhaM9.7-a (46% identical), Caenorhabditis elegans vha-17 (44% identical), Drosophila melanogaster VhaM9.7-b (40% identical), Drosophila melanogaster VhaM9.7-c (40% identical), and 1 more. Paralogues in human: ATP6V0E1 (70% identical).
Diseases named in the same sentence as ATP6V0E2 in open-access papers:
ATP6V0E2 is named in the same sentence as 3 diseases in open-access papers, as found by Europe PMC text mining. Sharing a sentence is not in itself a finding about the gene and the disease. The quoted sentences say what the papers report.
colon cancer (1 paper, 2020). "Through transcriptome sequencing, we found for the first time that anlotinib treatment upregulates ATP6V0E2 (ATPase H+ Transporting V0 Subunit E2) and other lysosome-related genes expression in human colon cancer." (PMID 32839434, 2020).
Parkinson disease (1 paper, 2025). A progressive degenerative disorder of the central nervous system characterized by loss of dopamine producing neurons in the substantia nigra and the presence of Lewy bodies in the substantia nigra and locus coeruleus. "In contrast, the Amyg showed upregulation of genes linked to oxidative phosphorylation (Atp6v1e1, Atp5mc2, Atp6v0e2), Parkinson disease (Snca, Calm1, Slc39a10), and regulation of actin cytoskeleton (Arpc3, Nckap1, Cfl1), indicating increased mitochondrial metabolism and structural plasticity." (PMID 41394722, 2025).
ATP6V0E2 also shares sentences with these, for which no sentence is quoted: cancer (1 paper).